ABL2 (ABL proto-oncogene 2, non-receptor tyrosine kinase)
Description:
Non-receptor tyrosine-protein kinase that plays an ABL1-overlapping role in key processes linked to cell growth and survival such as cytoskeleton remodeling in response to extracellular stimuli, cell motility and adhesion and receptor endocytosis. Coordinates actin remodeling through tyrosine phosphorylation of proteins controlling cytoskeleton dynamics like MYH10 (involved in movement); CTTN (involved in signaling); or TUBA1 and TUBB (microtubule subunits). Binds directly F-actin and regulates actin cytoskeletal structure through its F-actin-bundling activity. Involved in the regulation of cell adhesion and motility through phosphorylation of key regulators of these processes such as CRK, CRKL, DOK1 or ARHGAP35. Adhesion-dependent phosphorylation of ARHGAP35 promotes its association with RASA1, resulting in recruitment of ARHGAP35 to the cell periphery where it inhibits RHO. Phosphorylates multiple receptor tyrosine kinases like PDGFRB and other substrates which are involved in endocytosis regulation such as RIN1. In brain, may regulate neurotransmission by phosphorylating proteins at the synapse. ABL2 also acts as a regulator of multiple pathological signaling cascades during infection. Pathogens can highjack ABL2 kinase signaling to reorganize the host actin cytoskeleton for multiple purposes, like facilitating intracellular movement and host cell exit. Finally, functions as its own regulator through autocatalytic activity as well as through phosphorylation of its inhibitor, ABI1. Positively regulates chemokine-mediated T-cell migration, polarization, and homing to lymph nodes and immune-challenged tissues, potentially via activation of NEDD9/HEF1 and RAP1 (By similarity).
Synonyms: ABLL; ARG
Tractability: Small molecule: a structure with a bound ligand is known; a high-quality ligand is known; it has a high-quality binding pocket; it belongs to a druggable protein family. Antibody: its Gene Ontology location is reachable by antibodies, with medium confidence. PROTAC: it is named in the literature on targeted protein degradation; UniProt records ubiquitination sites on it; ubiquitination databases record sites on it; its protein half-life has been measured; a small molecule that binds it is known.
Target class: Tyrosine protein kinase Abl family; Protein Kinase; TK protein kinase group; Enzyme; Kinase
Gene: Protein-coding gene on chromosome 1 (179,099,330 to 179,229,684, reverse strand). Ensembl gene ENSG00000143322.
Subcellular location: Cytoplasm, cytoskeleton
Subcellular location (Human Protein Atlas): Cytosol; Intermediate filaments
Pathways (Reactome):
Signal Transduction: RAC1 GTPase cycle; RAC3 GTPase cycle
Developmental Biology: Role of ABL in ROBO-SLIT signaling
Immune System: Negative regulation of FLT3
Gene Ontology:
Molecular function: enzyme activator activity; enzyme binding; magnesium ion binding; manganese ion binding; phosphotyrosine residue binding; protein binding; protein tyrosine kinase activity; actin filament binding; actin monomer binding; non-membrane spanning protein tyrosine kinase activity; protein kinase activity; ATP binding
Biological process: cellular response to oxidative stress; cellular response to retinoic acid; peptidyl-tyrosine phosphorylation; phospholipase C-activating G protein-coupled receptor signaling pathway; positive regulation of cytosolic calcium ion concentration; positive regulation of neuron projection development; epidermal growth factor receptor signaling pathway; exploration behavior; negative regulation of Rho protein signal transduction; positive regulation of establishment of T cell polarity; positive regulation of T cell migration; protein modification process; regulation of actin cytoskeleton organization; regulation of autophagy; regulation of cell adhesion; regulation of cell motility; regulation of endocytosis; signal transduction
Cellular component: actin cytoskeleton; cytosol; plasma membrane; cytoskeleton
Genetic constraint (gnomAD): Loss-of-function variants: 48 observed, 105.57 expected, observed/expected ratio (o/e) 0.45, 90% interval 0.36 to 0.58. The upper end of that interval is the gene's LOEUF score, 0.58, which puts it in group 2 of 6, group 1 being the genes least tolerant of losing a copy. Missense variants: 1,239 observed, 1,492.9 expected, observed/expected ratio (o/e) 0.83, 90% interval 0.79 to 0.87. Synonymous variants: 543 observed, 560.28 expected, observed/expected ratio (o/e) 0.97, 90% interval 0.9 to 1.04.
Homologues: Orthologues: chimpanzee ABL2 (99% identical), macaque ABL2 (99% identical), dog ABL2 (97% identical), pig ABL2 (96% identical), guinea pig ABL2 (95% identical), mouse Abl2 (95% identical), rat Abl2 (91% identical), rabbit ABL2 (90% identical), tropical clawed frog abl2 (71% identical), zebrafish abl2 (67% identical). Paralogues in human: ABL1 (52% identical), FYN (18% identical), LCK (18% identical), SRC (18% identical), YES1 (18% identical), FGR (18% identical), BLK (18% identical), HCK (17% identical), FRK (17% identical), TNK2 (17% identical), TEC (17% identical), LYN (17% identical), and 20 more.
Diseases named in the same sentence as ABL2 in open-access papers:
ABL2 is named in the same sentence as 66 diseases in open-access papers, as found by Europe PMC text mining. Sharing a sentence is not in itself a finding about the gene and the disease. The quoted sentences say what the papers report.
breast carcinoma (17 papers, 2013 to 2025). "They include associations of methylation of regions of the ABL2 oncogene in breast cancer and in COAD/READ, and of the epidermal growth factor receptor EGFR gene in CLLE." (PMID 33676569, 2021). "Ras signaling pathway is the pathway which ABL1 and ABL2 belong to and it is known that Ras signaling pathway activation is implicated in breast cancer invasion and growth." (PMID 28361687, 2017). "However, the effect of ABL2 expression seems to some extent to be context dependent, since in a breast cancer model, loss of ABL2 accelerated tumor growth by enhancing cell proliferation." (PMID 28086240, 2017). "Overexpression of ABL2 promotes tumor metastasis in various cancers (e.g., breast cancer, lung cancer) by regulating the cytoskeleton and signaling pathways." (PMID 40282426, 2025). "Using machine learning algorithms on multi-omics data from over 6,000 breast cancer patients, we identified six key genes significantly associated with VM and patient risk scores: EP300, PIK3CA, DMXL1, LS, ABL2, and CDK4." (PMID 39165361, 2024). "In a mouse xenograft model using MDA-MB-231 breast cancer cells, ABL2 knockdown resulted in larger primary tumor size, but decreased invasion, intravasation, and spontaneous metastasis to the lungs." (PMID 34022881, 2021). "Knocking down of ABL2 in breast cancer cells (using a mouse xenograft model) leads to increased tumor cell proliferation and a significantly enlarged tumor size in breast cancer." (PMID 34512726, 2021). "While the effects of ABL1 or ABL2 inhibition has mixed effects on primary breast tumor growth, genetic or pharmacologic inhibition of the kinases impairs breast cancer metastasis." (PMID 34022881, 2021). "Inhibition of NRTKs in the PTK2B-Src-ABL2-cortactin cascade, in particular of ABL2, effectively inhibits the invadopodia-mediated invasiveness and metastasis of human breast cancer cells in a mouse tumor model." (PMID 35008569, 2021). "Knockdown of ABL2 in breast cancer cells resulted in decreased spontaneous metastasis to the lungs following orthotopic implantation of breast tumors in the mammary fat pad." (PMID 34022881, 2021). "Similar reports, concerned with prostate cancer and breast cancer, also reported that ABL2 promotes cancer cells invasion and migration." (PMID 29875348, 2018). "ABL2 promotes proliferation of breast cancer cells and recombinant 293 T cells, and Bmx is involved in angiogenesis and in regulation of the actin cytoskeleton and cell motility." (PMID 28659168, 2017). "The authors evaluated the result of single- or double-knockdown of ABL1 and ABL2 in breast cancer cells using RNA-seq analysis to reveal the signaling pathways required for ABL kinases-dependent bone metastasis." (PMID 28361687, 2017). "HOTAIR increased breast cancer invasiveness and metastasis by inducing positive regulators of cancer metastasis (ABL2 SNAIL, LAMB3 and LAMC2) in a manner dependent on PRC2." (PMID 23936419, 2013). "Although ABL2 has been studied in hepatocellular carcinoma, breast cancer, lung adenocarcinoma, and diabetic nephropathy, the function and detailed effect of ABL2 on GC remains unclear." (PMID 36104322, 2022). "Notably, a recent report also mentioned that loss of function of ABL1 and/or ABL2 does not inhibit breast cancer metastasis to the lung, which further demonstrated that ABL does not play crucial roles in the anti-metastatic function of Ponatinib." (PMID 29667003, 2019). "One gene targeted by hsa-miR-584-5p – FOXA1 – and two genes targeted by hsa-miR-570-3p – ABL2 and SUB1 – have been described in previous breast cancer studies." (PMID 34512726, 2021). "Single knockdown of either ABL1 or ABL2 in triple-negative breast cancer cells impaired anchorage independent growth, while expression of a constitutively active form of ABL1 in 4TI murine mammary tumors inhibited tumor growth." (PMID 34022881, 2021).
breast carcinoma (continued). "We next sought to determine a connection between mRNA expression levels of ABL1, ABL2, and CTTN in breast tumors to overall survival (OS) and disease-free survival (DFS) of breast cancer patients." (PMID 29774130, 2018). "Together, these observations suggest that overexpression of ABL2 and CTTN, either individually or synergistically, is correlated with breast cancer metastasis and poor patient prognosis." (PMID 29774130, 2018). "The correlation between an increase in ABL1 and ABL2 protein levels, which is not accompanied by a similar association in distant metastasis free survival (DMFS) suggests contrasting roles for the two kinases in promoting breast cancer metastasis." (PMID 29774130, 2018). "β1 integrin recruits the non-receptor tyrosine kinase Arg (Ableson-related gene, also known as Abl2) and stimulates the Arg-dependent phosphorylation of p190RhoGAP at the leading edge of fibroblasts; however, whether this occurs in breast cancer cell invadopodia has not yet been elucidated." (PMID 34531530, 2021).
lung adenocarcinoma (6 papers, 2016 to 2024). A carcinoma that arises from the lung and is characterized by the presence of malignant glandular epithelial cells. "Data from The Cancer Genome Atlas (TCGA) showed alterations of ABL1 and ABL2 in human lung adenocarcinomas, including copy number enhancement of ABL2 and somatic mutations in ABL1 in 1-2% of patients." (PMID 30956771, 2019). "Activated TAZ in lung adenocarcinoma cells elicits the expression of a panel of target genes that promote brain metastasis, including ABL2, AXL, and L1CAM." (PMID 37835395, 2023). "ABL2 expression and function have been studied in hepatocellular carcinoma, colorectal cancer, lung adenocarcinoma, and melanoma." (PMID 36104322, 2022). "ABL2 targets distinct transcriptional regulatory networks that include the heat shock factor 1 (HSF1) in lung adenocarcinoma cells to drive brain colonization through increased lung cancer cell survival and outgrowth." (PMID 34022881, 2021). "Further, we found that the ABL2 tyrosine kinase promoted TAZ nuclear accumulation and transcriptional activation in lung adenocarcinoma cells." (PMID 37835395, 2023). "Interestingly, it was found that ABL2 and TAZ activate an autocrine signaling loop during lung adenocarcinoma metastasis to promote colonization of the brain parenchyma." (PMID 34022881, 2021). "Expression of ABL2 was increased in H810 and H1048 cells, but there was no relative increase observed in H1355 cells, compared to other lung adenocarcinoma cell lines that lacked ABL2 amplification (Fig EV2C)." (PMID 26758680, 2016). "To determine whether lung cancer cells containing ABL2 amplifications are sensitive to ABL inhibitors, we utilized two lung adenocarcinoma cell lines (H810 and H1355) and a small cell lung cancer cell line (H1048), all harboring ABL2 amplifications, and subjected to treatment with imatinib." (PMID 26758680, 2016).
chronic myeloid leukemia (5 papers, 2017 to 2021). "Apart from its established role in chronic myeloid leukemia, studies have also suggested that amplification or overexpression of Abl1 and Abl2 is related to different carcinomas and related to solid tumors." (PMID 34840927, 2021). "Examples include the US Food and Drug Administration (FDA)-approved dasatinib used to target Abelson related kinase (Abl2) in chronic myeloid leukemia (CML)." (PMID 28925954, 2017). "While Imatinib is a well-known inhibitor for various tyrosine kinases such as ABL1, ABL2, KIT, and PDGFR and has been used to treat chronic myelogenous leukemia and solid tumors, little is known about how it can affect intracellular bacterial infections." (PMID 34782676, 2021).
leukemia (5 papers, 2005 to 2022). A malignant (clonal) hematologic disorder, involving hematopoietic stem cells and characterized by the presence of primitive or atypical myeloid or lymphoid cells in the bone marrow and the blood. "When comparing the targets between Dasatinib and imatinib/nilotinib, there are six common target kinases: Kit, PDGFR, ABL1, DDR1, ARG (ABL2), and the fusion kinase present only in certain leukemias, BCR-Abl." (PMID 36338985, 2022). "Although Abl1 and Abl2 are well known for driving leukemia development, their role in solid tumors has been appreciated only recently." (PMID 24223753, 2013). "Acute myeloid leukemia is prioritized as the most significant m6A associated disease, where m6A-regulated genes NSD1, PICALM, and ABL2 are OMIM-annotated disease genes, suggesting that they may be potential m6A-associated biomarkers in leukemia." (PMID 30601803, 2019). "Disruption of autoinhibition, such as by translocation of Abl1 or Abl2 next to a variety of different genes (e.g. Bcr, Tel, ETV6), leads to constitutive activation, which drives malignancies, particularly leukemias." (PMID 24223753, 2013).
lung carcinoma (5 papers, 2016 to 2025). "Both ABL1 and ABL2 kinases are required for metastasis of MSC-primed lung cancer cells to distal sites following intracardiac injection in mouse models." (PMID 34022881, 2021). "Following intracardiac injection of non-small cell lung cancer (NSCLC) cells in preclinical mouse models, it was found that the ABL kinases, specifically ABL2, drove metastasis of lung cancer cells to distal sites in the body including the brain." (PMID 34022881, 2021). "We previously showed that the ABL family of tyrosine kinases, ABL1 and ABL2, promote metastasis by breast and lung cancer cells in mouse models through activation of transcription factor networks." (PMID 33119681, 2020). "More recently, we uncovered a lung cancer cell-intrinsic feed-forward ABL2-TAZ-AXL signaling axis that promotes lung adenocarcinoma metastasis to the brain." (PMID 33119681, 2020). "Control (SCR) and ABL1+ABL2 knockdown (AA) lung cancer cells were co-cultured with MSCs and then implanted in mice by intracardiac injection." (PMID 33119681, 2020). "The ABL kinases, ABL1 and ABL2, promote invasion and metastasis of breast and lung cancer cells." (PMID 33119681, 2020). "To determine whether somatically mutated ABL1/2 may be required to maintain lung cancer cell survival, we treated this panel of NSCLC cancer cell lines harboring mutations in either ABL1 or ABL2 (H1915, H2110, H650, and H1623), with ABL inhibitors, and monitored cell viability." (PMID 26758680, 2016). "Efficient knockdown of ABL1 and ABL2 proteins and decreased phosphorylation of the ABL substrate p-CrkL was observed in both PC9 and HCC827 lung cancer cells." (PMID 33119681, 2020). "Treatment with imatinib moderately suppressed colony formation, only in the H810 cells, suggesting ABL2 amplification will not be a potent driver in lung cancer (Fig EV2D)." (PMID 26758680, 2016). "Depletion of ABL1 and ABL2 protein kinases in PC9-AA and HCC827-AA lung cancer cells impaired the increase of MMP9 but not MMP2 gelatinase activity induced by MSCs." (PMID 33119681, 2020).
melanoma (5 papers, 2012 to 2026). A malignant, usually aggressive tumor composed of atypical, neoplastic melanocytes. "Enhanced ABL2 expression and activation have been detected in multiple malignancies, including breast, colon, lung, and kidney carcinomas as well as melanoma." (PMID 41602364, 2026). "ABL1 promotes melanoma invasion through STAT3-dependent MMP1 expression, while ABL2 promotes melanoma invasion by increased expression of MMP-1, MMP-3, and MT1-MMP independently of STAT3." (PMID 34022881, 2021). "ABL1 and ABL2 promote invasion and metastatic progression of melanomas in part by activating the transcription factors Ets1, Sp1, and NF-κB/p65 which induce expression of cathepsin ECM proteases." (PMID 34022881, 2021). "Among the up-regulated oncogenes in melanoma, ABL2, NRAS, PDGFC and FGF1 have been reported to be melanoma-associated oncogenes." (PMID 22295108, 2012). "We used the lowest dose of SU6656 that efficiently reduces SFK activity in melanoma cells (10 μM), and we previously showed that this dose has no direct effect on ABL1 or ABL2 as it does not reduce their activities in cells that lack SFK expression." (PMID 33122628, 2020).
gastric cancer (4 papers, 2019 to 2024). A primary or metastatic malignant neoplasm involving the stomach. "And ABL2 could suppress cancer progression in prostate cancer, cervical carcinoma and glioma, whereas promoting hepatocellular carcinomas and gastric cancer progression." (PMID 37407973, 2023).
prostate carcinoma (4 papers, 2013 to 2024). A carcinoma that arises from epithelial cells of the prostate gland. "Our data suggests that c-Abl protooncogene and Abl2/Arg are important functional targets of miR-4723 in prostate cancer." (PMID 24223753, 2013). "c-Abl and/or Abl2 expression was significantly increased (assessed by immunohistochemistry [IHC]) in various tumors including prostate cancer." (PMID 24223753, 2013). "The main reason for a relatively low ABL2 could be the control by miRNAs (miR-30a-5p—in LUAD, miR-4723—in prostate cancer, miR-425-5p—in esophageal squamous cell carcinoma, lung and colon cancer, etc.)targeting ABL2 mRNA." (PMID 39329988, 2024). "Studies suggest that activation of c-Abl/Abl2 promotes prostate cancer progression." (PMID 24223753, 2013). "In addition, our study has identified a new miRNA based mechanism regulating Abl1 and Abl2 expression in prostate cancer." (PMID 24223753, 2013). "Accumulating evidence suggests that activation of c-Abl/Abl2 promotes prostate cancer progression." (PMID 24223753, 2013).
Acute Lymphoblastic Leukaemia (3 papers, 2020 to 2026). "ABL2 rearrangements represent a subtype of acute lymphoblastic leukaemia (ALL) associated with poor prognosis and survival." (PMID 41782643, 2026). "ABL1 kinase, a member of the Abelson kinase family that also includes ABL2, has been implicated in cancer, particularly in hematological malignancies such as acute myeloid leukemia (AML), chronic myeloid leukemia (CML), and lymphoblastic leukemia." (PMID 34361750, 2021). "Leukemogenic ABL proto-oncogene 2 kinase (ABL2) fusion proteins RCSD1-ABL2 and ZC3HAV1-ABL2 have been reported in Philadelphia chromosome-like acute lymphoblastic leukemia patients." (PMID 33233470, 2020).
cervical carcinoma (3 papers, 2023 to 2024). A carcinoma arising from either the exocervical squamous epithelium or the endocervical glandular epithelium. "This network identified mir-125a-5p as targeting ABL2, with a previous study reporting that the miR-125a-5p/ABL2 axis plays a crucial role in suppressing the proliferation and migration of cervical carcinoma." (PMID 37122729, 2023).